BCL9L (BCL9 like)
Description:
Transcriptional regulator that acts as an activator. Promotes beta-catenin transcriptional activity. Plays a role in tumorigenesis. Enhances the neoplastic transforming activity of CTNNB1 (By similarity).
Synonyms: DLNB11; B9L; Bcl9-2
Tractability: Small molecule: a structure with a bound ligand is known. PROTAC: UniProt records ubiquitination sites on it; ubiquitination databases record sites on it.
Gene: Protein-coding gene on chromosome 11 (118,893,875 to 118,925,926, reverse strand). Ensembl gene ENSG00000186174.
Subcellular location: Nucleus
Subcellular location (Human Protein Atlas): Nucleoplasm; Nucleoli fibrillar center
Pathways (Reactome):
Signal Transduction: Deactivation of the beta-catenin transactivating complex; Formation of the beta-catenin:TCF transactivating complex
Gene Ontology:
Molecular function: beta-catenin binding; transcription coactivator activity
Biological process: negative regulation of transforming growth factor beta receptor signaling pathway; positive regulation of epithelial to mesenchymal transition; positive regulation of transcription by RNA polymerase II; regulation of cell morphogenesis; canonical Wnt signaling pathway
Cellular component: beta-catenin-TCF complex; fibrillar center; nucleoplasm; nucleus
Genetic constraint (gnomAD): Loss-of-function variants: 19 observed, 93.08 expected, observed/expected ratio (o/e) 0.2, 90% interval 0.14 to 0.3. The upper end of that interval is the gene's LOEUF score, 0.3, which puts it in group 1 of 6, group 1 being the genes least tolerant of losing a copy. Missense variants: 2,022 observed, 2,070.6 expected, observed/expected ratio (o/e) 0.98, 90% interval 0.94 to 1.01. Synonymous variants: 900 observed, 834.96 expected, observed/expected ratio (o/e) 1.08, 90% interval 1.02 to 1.14.
Cancer hallmarks: proliferative signalling (promotes); invasion and metastasis (promotes); genome instability and mutations (suppresses)
Homologues: Orthologues: chimpanzee BCL9L (99% identical), macaque BCL9L (99% identical), pig BCL9L (96% identical), dog BCL9L (96% identical), guinea pig BCL9L (95% identical), mouse Bcl9l (94% identical), rat Bcl9l (94% identical), rabbit BCL9L (90% identical), tropical clawed frog bcl9l (48% identical), zebrafish bcl9l (46% identical). Paralogues in human: BCL9 (34% identical).
Diseases named in the same sentence as BCL9L in open-access papers:
BCL9L is named in the same sentence as 45 diseases in open-access papers, as found by Europe PMC text mining. Sharing a sentence is not in itself a finding about the gene and the disease. The quoted sentences say what the papers report.
colon carcinoma (14 papers, 2016 to 2025). "Further studies implicated a role for BCL9L in the initiation of colon cancer as well as its involvement in the EMT process of this tumor entity." (PMID 27713160, 2016). "In colon cancer, miR-214 targeting BCL9L can inhibit proliferation, metastasis, and epithelial-mesenchymal transition by down-regulating Wnt signaling." (PMID 34818353, 2021). "Previous studies have reported that BCL9L can promote the occurrence and development of choriocarcinoma, breast cancer, colon cancer, and pancreatic cancer." (PMID 33117820, 2020). "The colonic tumours that formed in VillinCreERApcfl/flBcl9fl/flBcl9lfl/fl mice retained expression of both Bcl9 and Bcl9l, suggesting that BCL9/9l are required for colonic tumour growth following the loss of APC." (PMID 30760720, 2019). "To date, the role of BCL9L in malignancy has been studied mainly in colon cancer, where it was found to be a β-catenin interaction partner and to enhance its TCF-mediated transcription." (PMID 27713160, 2016). "Indeed, the requirement of BCL9L for activating Wnt signalling indicates an essential role in colon cancer and hepatocyte transformation." (PMID 35522942, 2022). "Similarly, BCL9L plays a critical role in stem cell maintenance in epithelial homeostasis and carcinogenesis through the canonical Wnt signaling pathway in colon cancer." (PMID 34693378, 2021). "Additionally, many other driver genes are frequently mutated in colon cancer, such as ARID1A, SOX9, FAM123B, BCL9L, RBM10, CTCF, and KLF5." (PMID 34912802, 2021). "Moreover, BCL9L is demonstrated to enhance β-catenin–mediated transcriptions and increase the abilities of proliferation and metastasis in breast and colon cancer cell lines." (PMID 33117820, 2020). "miR-22 targets BCL9L and restrains Wnt/β-catenin signaling, thereby limiting EMT-driven invasion and tumor progression in colon cancer cells." (PMID 41470858, 2025). "Deletion of Bcl9 and Bcl9l reduces colonic regeneration following acute colitis and decreases expression of Wnt target genes and ISC markers in colonic tumours generated by chemical carcinogenesis." (PMID 30760720, 2019). "Previous studies described BCL9L as an important co-activator of WNT signaling and its importance for β-catenin-/TCF-mediated transcription in colon cancer cells." (PMID 27713160, 2016). "BCL9L can act as a co-factor of WNT signaling in tumors and has been shown, when overexpressed, to promote tumor progression in mouse models of WNT-driven colon cancer." (PMID 27149842, 2016). "But in colon cancer, the WNT signaling was inhibited by miR-22 through targeting BCL9L." (PMID 34345013, 2021). "In colon carcinoma, Wnt responsiveness of BCL9 and BCL9L themselves has been proposed." (PMID 31440992, 2020).
colorectal cancer (13 papers, 2008 to 2026). A primary or metastatic malignant neoplasm that affects the colon or rectum. "Through genomic analysis of colorectal cancers and cell lines, we find frequent loss of heterozygosity and mutations in BCL9L in aneuploid tumors." (PMID 28073006, 2017). "Importantly, the gene signature of Bcl9/Bcl9L knockout cells is negatively associated with the high stemness subtypes of colorectal cancers and positively correlates with patient overall survival." (PMID 34545187, 2021). "BCL9L has previously been identified as a key mediator of aneuploidy tolerance in colorectal cancer, promoting genomic instability and tumor progression, a feature already recognized as a poor prognostic marker across several cancer types." (PMID 41051593, 2025). "Recent studies showed that the deletion of BCL9 and BCL9l in colorectal cancer was found to inhibit colon tumorigenesis driven by an abnormal Wnt signaling pathway." (PMID 36835467, 2023). "For example, knockout of Bcl9/Bcl9L in a mouse model of colorectal cancer has resulted in the reprogramming of cancer cells from a stemness state to differentiation manifested by the downregulation of EMT-related gene expression." (PMID 34545187, 2021). "Using a colorectal cancer cell line, this group demonstrated that BCL9L represses caspase-2 at the transcriptional level, resulting in lower protein levels." (PMID 33425918, 2020). "find that BCL9L is often genetically inactivated in human colorectal cancers with chromosomal instability." (PMID 28073006, 2017). "Yet, other transcription factors may also interact with Bcl9/Bcl9L and β-catenin to modulate their transcriptional output, as for example shown for the Tbx3-mediated promotion of colorectal cancer cell metastasis." (PMID 34545187, 2021).
bladder cancer (10 papers, 2022 to 2026). "A high mRNA level of BCL9L is associated with lower survival of bladder cancer patients (p = 0.0029)." (PMID 35628130, 2022). "BCL9L and Wnt/β-catenin signalling play an oncogenic role in bladder cancer cells and seems to be associated with BC progression." (PMID 35628130, 2022). "Furthermore, the Cancer Genome Atlas Study of Bladder Cancer 2017, whole-exome sequencing of 412 MIBC detected that BCL9L is mutated in 11 patients out of 412, indicating that BCL9L might have a role in bladder cancer." (PMID 35628130, 2022). "For instance, BCL9L, as a co-activator of β-catenin, shows that its upregulated expression can markedly enhance the activity of the Wnt/β-catenin pathway in bladder cancer cells, thereby promoting their proliferation, migration, and invasion." (PMID 41387479, 2025). "This was addressed by functional analysis of BCL9L in bladder cancer cells after knockdown experiments using siRNA technology." (PMID 35628130, 2022). "The mRNA expression of BCL9L was significantly upregulated in MIBC compared to ureters from non-bladder cancer patients (2.9-fold induction, p < 0.05)." (PMID 35628130, 2022). "The current study now suggests that BCL9L and ß-catenin also play an oncogenic role in bladder cancer." (PMID 35628130, 2022). "We investigated the effect of BCL9L on cell migration and invasion in bladder cancer cells in real-time using the xCELLigence RTCA system after transfection with siBCL9L." (PMID 35628130, 2022). "Since BCL9L has not yet been linked with bladder cancer, the human protein atlas platform was utilised to investigate the association of BCL9L in bladder cancer." (PMID 35628130, 2022). "A therapeutic approach that targets cancer stem cells through BCL9L/Wnt/β-catenin pathway might be a promising strategy against bladder cancer." (PMID 35628130, 2022). "The data shows that expression of BCL9L protein was predominantly increased in dysplastic urothelium and MIBC compared to NMIBC and non-dysplastic urothelium, suggesting an association with aggressiveness and tumour stage of bladder cancer cells." (PMID 35628130, 2022). "In this section, we utilised an animal model that is more analogous to human bladder cancer to ultimately substantiate the role of NAT10 in regulating the expression of targets such as BCL9L, SOX4 and AKT1 through ac4C modification, therefore, promoting BLCA progression." (PMID 35522942, 2022). "BCL9L knockdown significantly represses the proliferation of both Cal29 (2.1-fold reduction) and T24 (1.7-fold reduction) cells compared to siControl (p < 0.05), suggesting that BCL9L could promote the proliferation of bladder cancer cells." (PMID 35628130, 2022). "This suggests that overexpression of BCL9L is associated with poor survival and a high level of BCL9L might not be beneficial for patients with bladder cancer." (PMID 35628130, 2022). "In line with this, BCL9L/Wnt/β-catenin signalling might play a crucial role in the progression of BC through the maintenance of BC stem cells, suggesting that these BC stem cells be responsible for the heterogeneity of bladder cancer." (PMID 35628130, 2022). "NAT10 mediates ac4C modification of oncogenes (BCL9L, SOX4, and AKT1) in bladder cancer to enhance their mRNA stability, thereby promoting cancer cell malignant behaviors and stem-cell-like properties." (PMID 40999468, 2025). "In bladder cancer, NAT10 knockdown specifically attenuated mRNA ac4C modification, impairing translation efficiency of BCL9L/SOX4/AKT1 and accelerating degradation of BCL9L/SOX4 transcripts." (PMID 40881352, 2025). "The down-regulation of NAT10 results in the reduction of ac4C modification in specific regions of mRNA, impairing translational efficiency of BCL9L, SOX4, AKT1 as well as the stability of BCL9R and SOX5, thereby reducing bladder cancer burden." (PMID 38233839, 2024).
bladder cancer (continued). "NAT10 mediates ac4C acetylation of BCL9L, SOX4, and AKT1, enhancing their mRNA stability and promoting proliferation, migration, and stemness while inhibiting apoptosis in bladder cancer." (PMID 39640362, 2024). "To summarise, the dynamic accommodation of BCL9L, SOX4 and AKT1 transcripts mediated by NAT10‐dependent ac4C modification is critical for the progression of bladder cancer." (PMID 35522942, 2022). "We demonstrate that BCL9L exerts oncogenic effects on the proliferation and invasion of bladder cancer cells and the knockdown of BCL9 also reduced the proliferation, migration, and invasion of bladder cancer cells, suggesting similar oncogenic roles." (PMID 42316797, 2026). "Similarly, NAT10 stabilizes BCL9L, SOX4, and AKT1 transcripts in bladder cancer through 3'UTR ac4C modification, fueling proliferation and invasion." (PMID 40588654, 2025). "Survival analysis of BC patients indicates that high mRNA level of BCL9L is significantly correlated with worse overall survival in bladder cancer patients, suggesting that a BCL9L high level might not be beneficial in BC patients." (PMID 35628130, 2022). "In bladder cancer, BCL9L has not yet been analysed and it is not known whether it plays a role in BC progression." (PMID 35628130, 2022). "The localisation of BCL9L in bladder cancer cells is not known." (PMID 35628130, 2022).
breast cancer (9 papers, 2014 to 2023). A primary or metastatic malignant neoplasm involving the breast. "Apparently, the complete loss of Bcl9/Bcl9L impairs survival of mammary tumor cells, while the disruption of the β-catenin-Bcl9/Bcl9L-Pygopus chain of adapters only affects the tumorigenic behavior of the tumor cells." (PMID 34545187, 2021). "Together these results indicate that the complete loss of Bcl9 and Bcl9L function in mammary tumor cells provokes their apoptotic death." (PMID 34545187, 2021). "Database mining indicated that BCL9 and only to a lesser extent BCL9L are found mutated in breast cancers of patients." (PMID 34545187, 2021). "In breast cancer, depletion of BCL9L by knockdown experiments inhibits the cell proliferation of MCF7 cells, while overexpression of BCL9L promotes tumourigenicity in transgenic mice, confirming the oncogenic effect of BCL9L in cell culture and animal models." (PMID 35628130, 2022). "For example, the mechanism of action of BCL9L protein appears to be dependent on molecular subtypes of breast cancer and cell lines." (PMID 35628130, 2022). "Then, we detected the expression of BCL9L in soft and stiff tumor cells isolated from patients with breast cancer." (PMID 33274785, 2021). "To investigate the functional relevance of Bcl9 and Bcl9L during tumor progression and invasion, we genetically deleted both Bcl9 and Bcl9L genes in mammary tumor cells of MMTV-PyMT mice." (PMID 34545187, 2021). "To examine the relevance of Bcl9 and Bcl9L in tumor progression and invasion in breast cancer patients, we first analyzed the genetic alteration of both genes in breast cancer patient data (from TCGA-BRCA PanCancer Atlas data collection)." (PMID 34545187, 2021). "In summary the interaction of Bcl9/Bcl9L with Pygopus appears to play only a limited role in the regulation of breast cancer tumor progression." (PMID 34545187, 2021). "In fact, the mammary epithelial cell-specific transgenic expression of Bcl9L is sufficient to induce ductal-like mammary tumors in aged mice." (PMID 34545187, 2021). "Analysis of the expression of Bcl9 and Bcl9L revealed that both proteins are highly expressed during mammary tumor progression in MMTV-PyMT transgenic mic." (PMID 34545187, 2021). "The frequency of BCL9L gene amplification in different breast cancer subtypes is highest in basal and luminal B breast cancer subtypes, with less incidence in the other subtypes and none in normal-type breast cancer." (PMID 34545187, 2021). "Using the same TCGA breast cancer data set we also found that low expression levels of BCL9L gene were a prognostic marker in ER-PR- patients." (PMID 34545187, 2021). "Another study reported that BCL9L induced ER positive breast cancers in vivo by regulating the expression of ER through a β-catenin independent mechanism and predicted therapeutic response to tamoxifen." (PMID 26384318, 2015). "One study showed nuclear BCL9L expression to be significantly associated with high nuclear grade and the expression of HER2 in breast cancers." (PMID 26384318, 2015). "This agrees with the observation that BCL9L is expressed in the nuclei of invasive lesions in breast cancer tissues, suggesting that strong staining of BCL9L in the nucleus might be related to cancer progression." (PMID 35628130, 2022). "Interestingly, interfering with the β-catenin-Bcl9/Bcl9L-Pygo chain of adapters only partially impaired the transcriptional response of mammary tumor cells to Wnt3a and TGFβ treatments." (PMID 34545187, 2021). "We next assessed whether a mutation of the N-terminal domain in β-catenin, which abrogated the interaction with both Bcl9 and Bcl9L on the side of β-catenin, recapitulated the effects of B9/B9L-ΔHD2 in breast cancer progression." (PMID 34545187, 2021). "Moreover, it has been reported that BCL9L is a critical player in regulating estrogen receptor expression in breast cancer, notably, in a β-catenin independent manner." (PMID 34545187, 2021).
breast cancer (continued). "Thus, Bcl9 and Bcl9L may promote mammary tumor growth and metastasis formation in MMTV-PyMT mice in a rather moderate manner and by fine-tuning the expression levels of direct and indirect Wnt target genes." (PMID 34545187, 2021). "Evidence shows its involvement in promoting mammary tumor growth and metastasis in mice as well as its activation in hepatocellular carcinoma under hypoxic conditions, both through BCL9/BCL9L and Wnt pathway activation." (PMID 37627176, 2023). "We thus were motivated to investigate the specific contribution of Bcl9 and Bcl9L to β-catenin-mediated Wnt signaling and as a consequence to tumor progression in the MMTV-PyMT transgenic mouse model of breast cancer." (PMID 34545187, 2021). "With regard to its functional importance in human malignancies it has been shown earlier that BCL9L overexpression increases cell migration in MDCK cells and siRNA-induced BCL9L knockdown inhibited proliferation of MCF7 breast cancer cells." (PMID 27713160, 2016). "In oestrogen receptor alpha (ER) positive breast cancer, BCL9L mechanism is independent of Wnt/β-catenin, however, it is dependent on ER signalling." (PMID 35628130, 2022). "There have been a few reports on the role of BCL9L (BCL9-2 or B9L), BCL9 homolog, in breast cancer." (PMID 26384318, 2015). "How BCL9 and BCL9L contribute to the breast cancer progression is not clear." (PMID 34545187, 2021). "Together, the results indicate that Bcl9/Bcl9L modulate but are not critically required for canonical Wnt signaling in its contribution to breast cancer growth and malignant progression, a notion consistent with the “just-right” hypothesis of Wnt-driven tumor progression." (PMID 34545187, 2021). "However, in oestrogen receptor alpha positive breast cancer cell lines MCF7 and T47D, BCL9L promotes tumourigenicity independent of Wnt/β-catenin signalling, but through induction of the oestrogen receptor alpha signalling." (PMID 35628130, 2022). "In conclusion, the results show that Bcl9 and more prominently Bcl9L contribute to the initiation and maintenance of TGFβ-induced EMT and cell migration of cultured mammary tumor cells in vitro, but that they are not exclusive determinants of these TGFβ-induced processes." (PMID 34545187, 2021).